FAT1 (FAT atypical cadherin 1)
Diseases named in the same sentence as FAT1 in open-access papers (continued):
Sharing a sentence is not in itself a finding about the gene and the disease.
Erythema (1 paper, 2014). Redness of the skin, caused by hyperemia of the capillaries in the lower layers of the skin. "As it may have been expected, the skin coated with IMQ exhibited thickening, erythema and scales, in the fat-1 transgenic mice, however, these inflammatory effects were more mild than those in WT mice." (PMID 24718773, 2014).
glomerular disease (1 paper, 2025). "Mutations in the FAT1 gene have been increasingly recognized as contributors to both isolated and syndromic forms of glomerular disease." (PMID 41368354, 2025).
Hearing impairment (1 paper, 2021). A decreased magnitude of the sensory perception of sound. "However, a previously reported case with terminal deletion of chromosome 4q, corresponding to a heterozygous 6.9-Mb deletion in the 4q35.1–q35.2 region, including FAT1, presented with hearing impairment in addition to other features." (PMID 33418956, 2021). "However, further research is required to elucidate and determine the potential role of FAT1 in hearing impairment." (PMID 33418956, 2021).
Hepatitis (1 paper, 2016). Inflammation of the liver. "Concanavalin A (Con A) was administered intravenously to wild-type (WT) and fat-1 transgenic mice to induce T cell-mediated hepatitis." (PMID 27679638, 2016). "Next, we compared the serum levels of cytokines between Con A-treated WT and fat-1 transgenic mice to determine the protective role of endogenous n-3 PUFAs in Con A-induced hepatitis." (PMID 27679638, 2016). "We demonstrated that T-bet was greatly suppressed in the liver of fat-1 transgenic mice compared to their WT counterparts, suggesting that endogenous n-3 PUFAs could suppress the differentiation of Th1 cells in Con A-induced hepatitis." (PMID 27679638, 2016).
Impaired glucose tolerance (1 paper, 2022). An abnormal resistance to glucose, i.e., a reduction in the ability to maintain glucose levels in the blood stream within normal limits following oral or intravenous administration of glucose. "Our results showed that HF diet-fed fat-1 (Fat-1 HF) mice had significantly lower fasting glucose, and were also protected against impaired glucose tolerance observed in HF diet-fed WT (WT HF) mice." (PMID 36234919, 2022).
invasive ductal carcinoma (1 paper, 2023). "In ductal carcinoma in situ (DCIS) and invasive ductal carcinoma (IDC), FAT1 and β-catenin expression are positively correlated with each other, and FAT1(−), β-catenin(−) or FAT1(−)/β-catenin(−) suggest worse disease-free survival." (PMID 37147285, 2023).
ischemia (1 paper, 2023). A hypoperfusion of the BLOOD through an organ or tissue caused by a PATHOLOGIC CONSTRICTION or obstruction of its BLOOD VESSELS, or an absence of BLOOD CIRCULATION. "To test whether ischemia-induced angiogenesis is also controlled by FAT1, we examined endothelial cell density in sections of the mouse gastrocnemius muscle 14 days after induction of hind limb ischemia." (PMID 37031213, 2023).
Kidney Cyst (1 paper, 2016). Abnormal fluid filled sac within the kidney, either acquired or congenital. "We performed MO knockdown of fat1 in Wt1b::GFP transgenic zebrafish, in which pronephric kidney cysts can readily be visualized." (PMID 26905694, 2016).
kidney failure (1 paper, 2013). An acute or chronic condition that is characterized by the inability of the kidneys to adequately filter the blood. "Thus, cases of patients with severe FAT1 loss of functions and kidney failure might be fatal before onset of muscle dystrophy and might thus fail to be classified as FSHD." (PMID 23785297, 2013).
laryngeal carcinoma (1 paper, 2017). Carcinoma that arises from the laryngeal epithelium.
laryngeal squamous cell carcinoma (1 paper, 2025). A squamous cell carcinoma that arises from the larynx.
malignant glioma (1 paper, 2022). A grade III or grade IV glioma arising from the central nervous system. "The FAT1-ROS-HIF-1 signaling pathway is activated by the IDH1 mutation, which suppresses malignant glioma." (PMID 35609054, 2022).
medulloblastoma (1 paper, 2020). A malignant, invasive embryonal neoplasm arising from the cerebellum. "It was reported that cloning human adipose atypical cadherin 1 (FAT1) has an effect on the prognosis of medulloblastoma (MB), while the conclusion still needs to be further proved." (PMID 33181666, 2020).
mycosis fungoides (1 paper, 2025). Classical mycosis fungoides is the most common type of mycosis fungoides (MF), a form of cutaneous T-cell lymphoma, and is characterized by slow progression from patches to more infiltrated plaques and eventually to tumors. "The absence of clearly defined driver events in FAT1 and KMT2D aligns with the broader genomic heterogeneity observed in mycosis fungoides, which has been described as lacking a unifying mutational signature." (PMID 41008827, 2025).
myeloma (1 paper, 2025). "Recurrent lymphoid CH mutations (in FAT1, KMT2D, MGA, and SYNE1) and myeloma driver gene mutations (in ZFHX3 and DIS3) were found in the dominant clonal and subclonal plasma cell populations." (PMID 40152254, 2025). "Despite the distinct burden of subclonal mutations, some CH mutations were conservative among MM, AL, POEMS, and MGUS, including lymphoid and myeloid CH mutations, such as those in KMT2D, FAT1, MGA, and SYNE1, and myeloma driver genes like ZFHX3 and DIS3." (PMID 40152254, 2025).
papilloma (1 paper, 2017). A benign epithelial neoplasm that projects above the surrounding epithelial surface and consists of villous or arborescent outgrowths of fibrovascular stroma. "We noticed that an inflammatory response to UVB irradiation was significantly alleviated in the hairless fat-1+/− mice compared with that in the WT mice, which is associated with their relative resistance to UVB-induced papilloma formation." (PMID 28912452, 2017).
renal agenesis (1 paper, 2016). Renal agenesis (RA) is a form of renal tract malformation characterized by the complete absence of development of one or both kidneys (unilateral RA or bilateral RA respectively), accompanied by absent ureter(s). "It is also possible that a direct dosage effect of the comprised genes (for example, FAT1) lead to CDH and renal agenesis." (PMID 27036947, 2016).
retinal degeneration (1 paper, 2010). Degeneration of the retina. "Female transgenic mice expressing the VPP rhodopsin mutation, known to cause a retinal degeneration, were bred to male transgenic mice expressing the fat-1 gene, which can convert n6 to n3 polyunsaturated fatty acids (PUFA)." (PMID 20806040, 2010). "The purpose of the present study was to determine whether providing high levels of DHA in mice by expressing the fat-1 protein can protect against hereditary retinal degenerations caused by the VPP rhodopsin mutation." (PMID 20806040, 2010).
schwannoma (1 paper, 2020). A benign, usually encapsulated slow growing tumor composed of Schwann cells. "Particularly, ATM, accounting for 33% of the samples, was the most frequently mutated cancer-related gene in schwannoma, followed by CHD4, FAT1, KMT2D, MED12, NF2, and SUFU (>20%)." (PMID 33193598, 2020).
small cell lung carcinoma (1 paper, 2025). Small cell lung cancer (SCLC) is a highly aggressive malignant neoplasm, accounting for 10-15% of lung cancer cases, characterized byrapid growth, and early metastasis. "Phosphorylation proteomics data reveal that in FAT1-mutated small cell lung cancer, 24 phosphorylation sites of VIM exhibit significant increases." (PMID 41153737, 2025).
steroid-resistant nephrotic syndrome (1 paper, 2019). Nephrotic syndrome, occurring in the pediatric population, in which proteinuria does not normalize with administration of steroids; this condition is unresponsive to a minimum of four weeks administration of oral corticosteroids. "A study of steroid-resistant nephrotic syndrome (SRNS) identified underlying mutations in the gene FAT1 (FAT atypical cadherin 1) in some patients." (PMID 29502161, 2019).
Stillbirth (1 paper, 2023). Death of the fetus in utero after at least 22 weeks of gestation. "Though the study was limited in ascertaining de novo from inherited variants, due to unavailability of paternal DNA, genes were reported by the authors that are either lethal, known to cause disease, or increase stillbirth risk (e.g., CCR5, FAT1, FLNB, INPP5K, MYO1C, PLOD2)." (PMID 36800380, 2023).
T-cell neoplasm (1 paper, 2020). "In addition to epigenetic modifiers implicated in all subtypes of T-cell neoplasm (TET2, DNMT3A, KMT2D, KMT2C, SETD2), recurrent mutations of the FAT1 tumor suppressor gene were for the first time recorded in 39% of cases." (PMID 31028364, 2020).
thymic adenocarcinoma (1 paper, 2017).
tongue cancer (1 paper, 2021). A malignant neoplasm affecting the tongue.
tongue tumor (1 paper, 2025). "In an in vivo study using an orthotopic SCC1 tongue tumor‐bearing mouse model, FAT1 depletion mediated by LNP‐sgFAT1 led to a reduced tumor growth rate and smaller tumor size." (PMID 40407216, 2025). "Importantly, the additional loss of FAT1 enhanced the antitumor activity of CPI‐613 treatment in SCC1 tumors, as evidenced by a further decrease in tongue tumor growth and a reduced number of Ki67‐positive cells in tumor tissues." (PMID 40407216, 2025).
tumor (250 papers, 2011 to 2026). "FAT1, a member of the cadherin superfamily, is known to function as a tumor suppressor, and its loss has been associated with enhanced cell proliferation and metastatic potential 9-11." (PMID 41362743, 2026). "Within the HIPPO pathway, FAT1, a tumor suppressor gene involved in maintaining epithelial architecture and suppressing tumor progression, was more frequently mutated in TCGA‐CRC (30%) than in Korean CRC (14%)." (PMID 41522471, 2026). "Given its relevance, we then examined FAT1 mutations in pan-cancer datasets using cBioPortal, finding that FAT1 mutations occur in over 10% of nine tumor types (TCGA, PanCancer Atlas)." (PMID 41362743, 2026). "Loss-of-function mutations in the tumor suppressor gene FAT1 have been shown to drive tumor progression and enhance YAP/TAZ signaling." (PMID 40478800, 2025). "Loss of FAT1 function in tumor cells results in YAP/TAZ activation, and two major mechanisms have been described how loss of FAT1 function leads to dysregulated YAP/TAZ activity in tumors." (PMID 40478800, 2025). "Our data also explain previous observations of increase in YAP/TAZ protein levels after loss of FAT1 in tumor cells." (PMID 40478800, 2025). "In non–small‐cell lung cancer (NSCLC), the expression level of the Fat1 gene is associated with tumour‐initiating capacity." (PMID 40665579, 2025). "On the contrary, the reduction of FAT1 protein expression has been linked to the progression of BC, aggressive tumor behavior, and unfavorable prognoses." (PMID 40894036, 2025). "Mutations in the FAT1 gene (3.3%) have been implicated in RCC tumor progression through disruption of the Hippo signaling pathway, which controls tissue growth by regulating cell cycle pathways." (PMID 41465847, 2025). "Considering the important roles of FAT1 in tumor progression and treatment, this study developed a mutation-associated risk signature for LUAD patients." (PMID 40672387, 2025). "In this study, we observed that FAT1 expression is significantly decreased in tumor-associated LECs compared to LECs in normal tissues." (PMID 41230499, 2025). "Suppression of MIB2 expression in various tumor cells led to same effects as loss of FAT1 expression, including a decrease in YAP and TAZ ubiquitination, and degradation as well as an increase in YAP/TAZ protein levels and expression of YAP/TAZ target genes." (PMID 40478800, 2025). "Here, we report that loss of FAT1 in various tumor cells, including HNSCC cells, resulted in increased protein levels of the transcriptional regulators YAP and TAZ." (PMID 40478800, 2025). "In the present study, we report for the first time that loss of mutant FAT1 in HNSCC cells leads to tumor remission." (PMID 40407216, 2025). "We discuss potential molecular mechanisms underlying this transformation, with mutations in NF1, PBRM1, and FAT1 likely contributing to the tumor's atypical morphology and loss of melanocytic markers." (PMID 40125165, 2025). "Loss-of-function mutations in FAT1 result in aberrant Wnt activation, increased proliferation, and tumor progression." (PMID 41008827, 2025). "Patients with FAT1 mutations (including synonymous mutations) exhibited a higher tumor mutation burden (TMB) compared to wild-type patients (p < 0.001)." (PMID 40242237, 2025). "The presence of FAT1 mutations was associated with tumor spread (WPOI-5) (n = 7, 63.6% vs. n = 8, 18.2%; p = 0.005)." (PMID 41154345, 2025). "Meanwhile, patients with high expression of PCDHGB7 in LUSC were more likely to develop FAT1 mutations, which would contribute to tumor development." (PMID 39949775, 2025). "In cancer, the FAT1 mutation promotes metastasis, invasiveness, malignant progression, and tumor initiation." (PMID 39199674, 2024).
tumor (continued). "In OSCC as well, FAT1 is frequently mutated or downregulated, impairing its tumor-suppressing abilities." (PMID 39169426, 2024). "In LUSC, FAT1 promoter hypermethylation events reducing FAT1 expression levels and FAT1 copy number loss events were observed in the same tumours." (PMID 39738653, 2024). "FAT1 encodes a cadherin protein and tumor suppressor that controls organ growth, cell polarisation, and cell-cell contacts and is involved in tumor invasion, metastasis, and drug resistance." (PMID 38971800, 2024). "Numerous studies have documented frequent alterations in FAT1 across various cancer types, with its aberrant expression being linked to unfavorable survival rates and tumor progression." (PMID 38855103, 2024). "WGD events were highly prevalent in the lung TRACERx 421 cohort (84% of LUSC and 77% of LUAD) and FAT1 driver mutations were selected before WGD in LUSC tumours." (PMID 39738653, 2024). "FAT1 is one of the most frequently mutated TSGs in cancer whose LOF enhances tumor invasiveness, metastasis, and drug resistance, suggesting a link between APOBEC-induced protein truncations and disease outcomes." (PMID 37922356, 2023). "In CSCC, a loss in function of FAT1 promotes tumor initiation, progression, invasiveness, stemness, and metastasis through the induction of a hybrid EMT state." (PMID 37370836, 2023). "FAT1 is frequently mutated in human cancer and acts as an oncogene or tumor suppressor depending on the type of cancer." (PMID 37147285, 2023). "FAT1 is mutated in approximately 20% cases, and is associated with tumor progression and survival of HNSCC patients." (PMID 36979661, 2023). "As a tumor suppressor, the loss of FAT1 promotes resistance to CDK4/6 inhibitors via the Hippo pathway, which was expressed at low levels in the high-risk group among patients with HER2− BC." (PMID 37529698, 2023). "FAT atypical cadherin 1 (FAT1), a transmembrane protein, is frequently mutated in various cancer types and has been described as context-dependent tumor suppressor or oncogene." (PMID 36653435, 2023). "Here the tumour suppressor gene FAT1 contained a loss of heterozygosity with associated CN-dependent ASE in two tumour regions." (PMID 37046093, 2023). "Inactivating mutations in the tumor suppressor gene FAT1 have been shown to promote tumor growth and to increase YAP/TAZ signaling." (PMID 37031213, 2023). "In summary, the decrease or loss of CDH1 (E-cadherin gene), SMAD4, PTEN, and FAT1 expression leads to an aggressive tumor with an increased invasive phenotype and increased metastatic potential." (PMID 37687058, 2023). "FAT atypical cadherin 1 (FAT1) encodes a protocadherin, a gene frequently mutated in cancer, and it can act as an oncogene or a tumour suppressor gene, depending on the cancer type." (PMID 36615513, 2022). "The second most commonly mutated gene was FAT1, a tumor suppressor preventing cancer development, FAT1 promotes the migration of HCC cells by regulating the expression levels of EMT-associated genes." (PMID 35911687, 2022). "We revealed that FAT1 mutations in UCEC predicted a better prognosis for tumor patients, whereas they predicted poor survival in HNSC patients." (PMID 36517565, 2022). "We thus concluded that FAT1 expression level in various cancers is inversely associated with infiltration of tumor-inhibiting immune cells and positively associated with the level of tumor-promoting immune cells." (PMID 35720420, 2022). "For example, mutations in the known tumor suppressors FAT1 and FAT4 occurred only in patients S1 and S5." (PMID 36618022, 2022).